IL17A (interleukin 17A)
Diseases named in the same sentence as IL17A in open-access papers (continued):
Sharing a sentence is not in itself a finding about the gene and the disease.
bronchiolitis (10 papers, 2017 to 2024). Inflammation of the bronchioles characterized by swelling of the bronchioles and mucus accumulation. "Here, activation of the IL-17A pathway was associated with RV-only bronchiolitis compared to RSV-only bronchiolitis." (PMID 38410509, 2024). "sRNAs are known to downregulate their mRNA target, we found that, compared to those associated with RV-only bronchiolitis, sRNAs associated with RSV-only bronchiolitis may relatively activate the IL-6 and IL-8 pathways and relatively inhibit the IL-17A pathway." (PMID 38410509, 2024). "Here we show that elevated levels of pro-inflammatory cytokines (IL1β, IL6, TNFα, IL18, IL23), regulatory cytokines (IL10, IL17A) and IFNγ were found in the three bronchiolitis cohorts." (PMID 36561744, 2022). "Also, reduced IFN-γ levels were detected in children with moderate bronchiolitis; however, in children with severe bronchiolitis, the levels of IL-17A and MUC5AC were increased." (PMID 30936869, 2019). "In summary, bronchiolitis NLF displayed a pronounced pro-inflammatory cytokine profile, and the presence of the regulatory cytokines IL10 and IL17A, in the context of a predominant pro-inflammatory response suggests they participate in the local control of immunopathological injury." (PMID 36561744, 2022). "Additionally, there is a predicted relative activation of IL-17A in RV bronchiolitis compared to RSV bronchiolitis due to differential expression of bacterial sRNAs, leading to higher predicted neutrophil recruitment in RV-bronchiolitis, and comparatively less so in RSV-bronchiolitis." (PMID 38410509, 2024).
cholangitis (10 papers, 2013 to 2024). An acute or chronic inflammatory process affecting the biliary tract. "In contrast, the cholangitis in IL-17A−/− and IL-22−/− mice was significantly attenuated as evaluated by portal inflammation and bile duct damage." (PMID 24040208, 2013). "Since the occurrence of cholangitis was completely abrogated only in p40−/− mice but not in Th17-deficient mice (p19−/−, IL-17A−/− and IL-22−/−) and Th1-deficient p35−/− mice, we next attempted to determine the role of IFN-γ in the induction of cholangitis." (PMID 24040208, 2013).
chorioamnionitis (10 papers, 2016 to 2026). A morphologic finding indicating inflammation of the fetal sac membranes. "Cord blood of infants who were prenatally exposed to chorioamnionitis, a risk factor for BPD, contains higher frequency of IL-17a-expressing T lymphocytes." (PMID 37744375, 2023). "Moreover, in experimental model of chorioamnionitis, maternal exposure to LPS increases IL-17a expression in the offspring lung T lymphocytes." (PMID 37744375, 2023). "Interestingly, histological chorioamnionitis, a risk factor for BPD development, is associated with a higher frequency of IL-17a-expressing T lymphocytes in cord blood." (PMID 33117383, 2020). "Although amniotic fluid ILC3s produce IL-17A and TNFα, indicating their functionality, their numbers in patients with intra-amniotic infection/inflammation remain unchanged compared to those without this pregnancy complication." (PMID 30416502, 2018).
dermatomyositis (10 papers, 2013 to 2025). Dermatomyositis (DM) is a type of idiopathic inflammatory myopathy characterized by evocative skin lesions and symmetrical proximal muscle weakness. "In an MDA-5 amyopathic dermatomyositis–ILD patient, adding MMF (1.5 g/day) improved PF ratio and lowered FGF-2, CX3CL1, IL-1ra, IL-17A, IP-10 and MCP-1." (PMID 40650314, 2025).
dysplasia (10 papers, 2012 to 2025). A usually neoplastic transformation of the cell, associated with altered architectural tissue patterns. "We found that Helicobacter pylori is able to drive gastric IL-17 inflammation in gastric intestinal metaplasia and dysplasia in Helicobacter pylori-infected patients, and that IL-17A serum levels are significantly increased in patients with gastric intestinal metaplasia and dysplasia." (PMID 36980548, 2023). "Serum IL-17A, IL-23, and TNF-α increased at the inflammation and dysplasia stage, and the IL-23 dramatically elevated in the 6th week particularly." (PMID 35615089, 2022). "We also investigated the serum IL-17A levels in Helicobacter pylori patients with gastric intestinal metaplasia and dysplasia, and patients with Helicobacter pylori non-atrophic gastritis (NAG)." (PMID 36980548, 2023). "A significant increase in serum IL-17A was found in the peripheral blood of subjects with gastric intestinal metaplasia and dysplasia, compared to patients with non-atrophic gastritis and to controls." (PMID 36980548, 2023).
esophageal cancer (10 papers, 2020 to 2025). A primary or metastatic malignant neoplasm involving the esophagus. "Furthermore, our preliminary data demonstrated a positive correlation between ALDH2 and IL-17A expression in certain cancers, such as head and neck carcinoma, colon adenocarcinoma, and esophageal cancer." (PMID 38226171, 2024). "To understand why the downstream genes MMPs was negatively correlated with the upstream gene IL-17A in esophageal cancer, we next performed GSEA analysis on all DEGs of CR/pCR versus <CR/ <pCR to explore signaling pathways that might explain the correlation." (PMID 37609436, 2023). "Similarly, in the field of esophageal cancer, IL-17A can not only promote the invasion of tumor cells, but also induce anti-tumor immunity by recruiting and activating beneficial B cells and neutrophils." (PMID 37609436, 2023). "Though, the role of circulating IL-17 or IL-22 in esophageal cancers is not yet defined and further studies are needed to clarify the role of IL-17A and IL-22 in EACs." (PMID 32298379, 2020).
gastric adenocarcinoma (10 papers, 2013 to 2024). "Given that this investigation represents a pilot single-center study, future multi-center research activities dealing with serum IL-17A levels in gastric adenocarcinoma would be very important for a better definition of the test." (PMID 36980548, 2023).
giant cell arteritis (10 papers, 2012 to 2024). "This is in contrast to findings in SLE and giant cell arteritis (GCA) where a close relationship of IL-17A+ T cell numbers and disease activity is reported." (PMID 23079279, 2012). "It still needs further investigation to elucidate whether IL-17F contributes much less than IL-17A in mediating IL-17RA-downstream cascades for leukocyte recruitment and aortic inflammation in our model and KD-related arteritis." (PMID 38451335, 2024). "Studies in Giant Cell Arteritis (GCA), the other variant of LVV, have shown increased Th1 and Th17 (T-helper 17 cells, producing IL-17A) in peripheral blood and also elevated serum IFN-γ and IL-17A." (PMID 27034824, 2016). "The aim of this study was to examine the association of rs2275913 IL17A and rs2397084, rs11465553 and rs763780 IL17F gene polymorphisms with histopathological changes in transplanted kidney biopsies such as: glomerulitis, tubulitis, arteritis, cell infilitration and fibrosis." (PMID 30961540, 2019). "Anakinra (IL-1 receptor antagonist), ustekinumab (anti-IL-12/23p40 monoclonal antibody), and secukinumab (anti-IL-17A monoclonal antibody) have demonstrated the effectiveness in the treatment of giant cell arteritis in case reports, case series, and non-controlled cohort studies." (PMID 34066203, 2021).
glioblastoma (10 papers, 2016 to 2025). The most malignant astrocytic tumor (WHO grade IV). "While one study has evaluated IL-17A expression in glioblastoma, and found an association between increased IL-17A+ infiltrates and diminished OS, RORγt expression has not been evaluated in GBM." (PMID 34943886, 2021). "B. The levels of CCL20 and IL-17A in sera from CRC patients, lung adenocarcinoma [LUAD] patients, glioblastoma [GBM] patients and controls (Healthy donors [HD]) were tested by Elisa (*P < 0.05; **P < 0.01; ***P < 0.001)." (PMID 31387598, 2019).
intestinal tumors (10 papers, 2010 to 2024). "The adoptive transfer of Treg from IL-17A-deficient Apc/Min+ mice and Apc/Min+ iTreg also suggests that the reduced tumor burden and normal thymic development of T cells are important to control intestinal tumor multiplicity." (PMID 26146642, 2015). "The role of IL-17A in promoting the development of intestinal tumors has been extensively studied, and the removal of IL-17A has a significant impact in reducing the number of tumors in ApcMin mice." (PMID 39351241, 2024). "In intestinal tumor bearing model, the tumor size is significantly reduced in IL-17 gene-knockout mice compared with wide-type (WT) mice, and anti-IL-17A monoclonal antibody treatment results in decreased tumor size in the WT mice." (PMID 24382972, 2013).
keratitis (10 papers, 2012 to 2025). A corneal disease that is characterized by inflammation of the cornea. "Moreover, the development of Candida-induced keratitis is blocked by anti-IL-17A or anti-IL-23p19 antibodies and is defective in nude mice." (PMID 38312837, 2024).
Lyme borreliosis (10 papers, 2009 to 2022). "B cell immunity, including the chemokine CXCL13, has an established role in Lyme neuroborreliosis, and also, T helper (Th) 17 immunity, including IL-17A, has recently been implicated." (PMID 28148307, 2017). "By using a set of markers in addition to CXCL13 and IL-17A, we confirm that B cell- and Th17-associated immune responses are involved in Lyme neuroborreliosis pathogenesis with different patterns in subgroups." (PMID 28148307, 2017). "afzelii spirochetes induce significantly more IL-17A production by Lyme disease patients’ PBMCs compared to that induced by Bo." (PMID 34827938, 2021). "However, Lyme disease patients’ PBMC-derived IL-17A, IL-17F, and IL-22 proteins were induced by all three Borrelia species compared to unstimulated PBMCs, which highlights that Borrelia spp." (PMID 34827938, 2021). "In the unstimulated samples, the concentrations of cytokines in patients with Lyme neuroborreliosis were comparable with references, except interferon (IFN)-α, interleukin (IL)-17A, IL-1β and IL-8, which were all significantly below the references." (PMID 34041044, 2021). "IL-17A, CXCL1 and CCL20 have however been reported present in other Lyme borreliosis manifestations, such as Lyme arthritis (IL-17), erythema migrans and acrodermatitis chronica atrophicans (CXCL1 and CCL20)." (PMID 28148307, 2017).
metastatic melanoma (10 papers, 2008 to 2022). A melanoma that has spread from its primary site to another anatomic site. "patients with metastatic melanoma treated with tremelimumab (CTLA-4-targeted MAb), either alone or in combination with other types of immunotherapy, demonstrated increased numbers of circulating Th17 cells, measured as IL-17A-secreting CD4+ T cells following activation in vitro." (PMID 31616428, 2019).
myositis (10 papers, 2014 to 2025). "In contrast, predictive factors for PAH leading to a higher probability of death in patients with myositis have been described as age, infection, IL-17A level, anti-SRP antibody, and steroid monotherapy." (PMID 41517327, 2025). "We found higher serum levels of IL-10, IL-6, CXCL8, IL-1β, IL-33, IFN-γ, TNF-α, IL-23, and IL-17A in myositis patients compared to the HSs." (PMID 39456842, 2024). "Interleukin (IL)-17A, also known as IL-17, was detected in lymphocytic infiltrates in myositis tissues and IL-17 serum level was elevated in IIM patients." (PMID 30693003, 2018).
neurosyphilis (10 papers, 2014 to 2023). Infection of the brain or spinal cord by Treponema pallidum. "In another study, researchers detected changes in IL-1β, IL-4, IL-6, IL-10, IL-17A and IL-21 levels in the CSF of neurosyphilis patients before penicillin treatment." (PMID 36452956, 2022). "Here, we present a case of latent neurosyphilis manifesting after initiation of the immunosuppressive medication secukinumab, a monoclonal antibody that antagonizes interleukin-17A." (PMID 34650839, 2021). "In line with this notion, patients with prolonged symptoms after treatment of neurosyphilis had higher levels of IL-17A in CSF." (PMID 28148307, 2017). "Studies have shown that the level of IL-17A in the CSF of patients with asymptomatic neurosyphilis is significantly higher than that in patients without neurosyphilis." (PMID 36452956, 2022).
pneumococcal pneumonia (10 papers, 2011 to 2025). A febrile disease caused by STREPTOCOCCUS PNEUMONIAE. "Here, we show that bacterial lysates exert protection against pneumococcal pneumonia independently of neutrophils, IL-17A or Caspase-1/11 activation, suggesting the existence of redundant mechanisms of protection." (PMID 33981296, 2021). "Therefore, the ability of IL-27-mediated IL-17A suppression in γδ T cells to sensitize mice to secondary pneumococcal pneumonia was dependent upon STAT1." (PMID 24408967, 2014). "In order to identify whether there was some dysregulated production of IL-17A during secondary pneumococcal pneumonia, cytokine/chemokine/growth factor was measured in lung homogenates of mice infected with virus alone, S. pneumoniae alone or virus plus S. pneumoniae." (PMID 24408967, 2014). "Overall results indicate that on one hand PrtA/curdlan immunization activated antigen-specific antibody and IL-17A response in the mice, but on the other, it failed to protect against pneumococcal pneumonia and invasive infection." (PMID 30253765, 2018). "We saw that PrtA-specific IL-17A response was induced in the mice with curdlan as an adjuvant, but it did not protect against pneumococcal pneumonia." (PMID 30253765, 2018). "Interestingly, neutralization of IL-17A did not significantly change pulmonary pneumococcal burdens in WT mice, indicating that IL-17A was produced at a functionally ineffective level in WT mice during secondary pneumococcal pneumonia." (PMID 24408967, 2014).
syphilis (10 papers, 2012 to 2026). A contagious bacterial infection caused by the spirochete Treponema pallidum. "Therefore, it was confirmed that the IL17A polymorphisms rs2275913 and rs3819024, as well as the haplotype including these two SNPs, influenced syphilis susceptibility." (PMID 37937275, 2023). "Furthermore, the researchers also investigated whether IL17A rs2275913 and rs3819024 were linked to IL17A mRNA expression and secretion in syphilis patients." (PMID 37937275, 2023). "We prospectively recruited all patients with a new diagnosis of syphilis and tested their plasma for IFNα, IFNγ, IL-1β, IL-12p40, IL-12p70, IP-10, MCP-1, MIP-1α, MIP-1β, IL-4, IL-5, IL-6, IL-7, IL-8, IL-10 and IL-17A at baseline pre-treatment and 6 months following therapy." (PMID 28143443, 2017).
tularemia (10 papers, 2010 to 2025). Tularemia is an infection caused by the bacterium Francisella tularensis. "In summary, these data characterize the involvement and underline the protective key role of the IL-17A axis in the lungs from inhalational tularemia." (PMID 20585449, 2010). "In leporids, IL17A had been implicated in the host defense against extracellular pathogens, such as Francisella tularensis that infects hares and rabbits and causes the zoonotic disease tularemia." (PMID 26788019, 2015). "For instance, DNTs constitute a major responding T cell subset in murine lungs during Francisella tularensis infection, conferring protection via IL-17A and IFN-γ production." (PMID 40821846, 2025). "Here we provide evidence for the involvement of IL-17A in host defense to inhalational tularemia, using a mouse model of intranasal infection with the Live Vaccine Strain (LVS)." (PMID 20585449, 2010). "Similarly, IL-17A is required for the generation of protective IFNγ responses during pulmonary tularemia." (PMID 39772023, 2024). "Thus, considering the important biological role of the European rabbit immune response against several diseases, including tularemia, we performed a genetic characterization of IL17A in four leporid genera (Oryctolagus, Brachylagus, Sylvilagus, and Lepus)." (PMID 26788019, 2015). "The ability of IL-17A to regulate TH1 responses in the context of microbial infections is not limited to the tularemia model, with reports that IL-17 can influence adaptive immunity to pulmonary Chlamydia muridarum and Mycobacterium bovis BCG infection via similar mechanisms." (PMID 24586147, 2014). "Pulmonary infection of mice with the intracellular bacterium Francisella tularensis induced a protective TH17 response, and deletion of the IL-23/IL-17A axis, but not IL-17F or IL-22, increased susceptibility to pulmonary tularemia." (PMID 24586147, 2014). "However, although a role for IL-17 in facilitating neutrophil responses is well established, during pneumonic tularemia, recruitment of CD11b+Ly6G/C+ cells was not affected by the absence of IL-17A." (PMID 25101094, 2014).